CDA (cytidine deaminase)
Diseases named in the same sentence as CDA in open-access papers (continued):
Sharing a sentence is not in itself a finding about the gene and the disease.
cancer (continued). "Guadecitabine is more resistant than azacitidine or guadecitabine to degradation by cytidine-deaminase (CDA), and has greater incorporation into DNA of dividing cancer cells." (PMID 34360879, 2021). "The study revealed a novel positive correlation between gemcitabine sensitivity and levels of its active metabolites or protein expression ratios hENT1/CDA and hENT1 × DCK/CDA × DCTD in cancer cells." (PMID 33287390, 2020). "Expression analysis of the key enzymes that regulate gemcitabine uptake (hENT1) and intracellular metabolism (CDA, DCK, NT5C1A, and DCTD) was performed in cancer cells and PSCs by immunofluorescence and by western blot analysis using total cell lysates." (PMID 33287390, 2020). "Immunohistochemical analysis of the source tumors revealed strong positive staining for hENT1, CDA, DCK, and NT5C1A in the cancer cells, whereas minimal expression was detected in the stromal cells." (PMID 33287390, 2020). "Cancer cells have relatively high levels of CDA and TYMP, explaining the increased sensitivity of cancer cells to CPBN, and the low adverse effects of this drug on non-tumoral tissues." (PMID 30740528, 2019). "Overall, we suggest CDA and P2Y6 as potential targets for cancer immunotherapy." (PMID 38844817, 2024). "Of note, the in vivo levels of Pdcd1 (encoding PD-1) or Cd274 (encoding the PD-1 ligand PD-L1), both in vivo and in cultured cancer cells, were not altered by CDA depletion." (PMID 38844817, 2024). "We detected no CDA deficiency, in terms of either protein activity or mRNA levels, in samples from patients relative to those from controls, and were therefore unable to confirm our initial hypothesis of a relationship between CDA deficiency and cancer predisposition." (PMID 35982128, 2022). "Cytosine deaminase (CDA) mediating the conversion of non-toxic prodrug 5-fluorcytosine (5-FC) into toxic drug 5-fluorouracil (5-FU) has been recognized as a powerful cancer-therapeutic approach comparing to the traditional chemotherapies and radiotherapies." (PMID 36164544, 2022). "In this family, all APOBEC3s, except for APOBEC3B, APOBEC3D, APOBEC3F, and APOBEC3G, contain only one CDA, which may explain why APOBEC3B is an epigenetic factor in many cancers." (PMID 36203448, 2022). "Perhaps gemcitabine concentration is so low in these cancer cells that no survival benefit for the patient is offered, hence there is no benefit to be lost by the action of CDA." (PMID 34830914, 2021). "Furthermore, the key gemcitabine regulators hENT1, DCK, CDA, and NT5C1A were expressed to varying degrees among the different cancer cells, whereas PSCs displayed overall significantly lower expression than the cancer cells." (PMID 33287390, 2020). "Comparison of gene expression between the editing-positive and -negative samples showed that APOBEC3A was the only CDA gene whose expression was upregulated in the editing-positive samples in all three cancers." (PMID 25898173, 2015). "Three different carcinoma cell lines (MIAPaCa-2, H441, and H1299) exhibited decreased cell proliferation after sole administration of THU, while being unaffected by knocking down CDA." (PMID 22616006, 2012). "Moreover, in silico data analyses revealed that, for some cancers, such as pancreatic, lung, stomach or rectum adenocarcinomas, patients with tumors displaying little or no CDA expression have a better prognosis." (PMID 35925417, 2022). "Altogether, developing a non-cell permeable CDA inhibitor or a method to remove plasma CDA may be of immediate use in cancer patients not responding to cytidine analogues and, also perhaps to improve the therapeutic index of DHODH inhibitors." (PMID 36424385, 2022). "In cancer cells, aberrations of the copy number of the CDA gene are not reported." (PMID 35582220, 2020).
cancer (continued). "Cytosine deaminase (CDA) is a non-mammalian enzyme with powerful activity in mediating the prodrug 5-fluorcytosine (5-FC) into toxic drug 5-fluorouracil (5-FU), as an alternative directed approach for the traditional chemotherapies and radiotherapies of cancer." (PMID 36164544, 2022). "In cancer cells, gemcitabine-induced cytotoxicity was significantly lower following knockdown of hENT1 and DCK, whereas knockdown of CDA and NT5C1A had no impact, highlighting the importance of a balanced expression of the key regulators of gemcitabine metabolism for treatment effects to occur." (PMID 33287390, 2020). "CDA synergizes with PmTriTNE to eliminate triple‐negative breast cancer (TNBC), especially cancer stem cells (CSCs) and coordinate innate and adaptive immunity to achieve whole cancer immunity cycle cascade amplification against heterogeneous TNBC and generate a vaccination effect." (PMID 36089659, 2022).
infection (17 papers, 2005 to 2026). The state of being infected such as from the introduction of a foreign agent such as serum, vaccine, antigenic substance or organism. "A3Z1 is a host cytidine deaminase that mutates DNA viral genomes before integration, thereby restricting infection." (PMID 32365702, 2020). "As a hallmark of hA3G’s cytidine deaminase activity, the virion-associated hA3G causes G to A hypermutation in viral genome during the new round of infection." (PMID 29795228, 2018). "A3G is encapsidated into progeny virions and exerts its potent antiviral effects upon infection in a new cell by reducing cDNA production, inducting G-to-A hypermutations in the viral genome through its cytidine deaminase activity and causing defects in integration into the host genome." (PMID 38793610, 2024). "The HIV-1 Vif protein counteracts viral hypermutation caused by the host cytidine deaminase APOBEC3G (A3G), ensuring productive infection." (PMID 41280050, 2025). "Previous reports have shown that viruses, including MMTV, use LPS on bacterial cells to facilitate infection, yet this signal likely will increase cytidine deaminase levels that curtail virus replication, necessitating Rem degradation of AID." (PMID 39208378, 2024). "Following immune response or infection within the body, activation of T cell‐dependent and T cell‐independent antigens triggers the activation of activation‐induced cytidine deaminase, initiating the CSR process." (PMID 39144468, 2024). "The presence of cdba or activation induced cytidine deaminase hints further class switching in the germinal centers post infection." (PMID 38698863, 2024). "Down-regulated features for snails with 3d infections again included cytidine deaminase, FREP12 precursors, and TLR 4 and 8 among others." (PMID 29045404, 2017). "Several studies, including our own, have shown that A3 proteins inhibit infection by cytidine deaminase-independent means, including inhibiting reverse transcription." (PMID 24851906, 2014). "In mice, this approach has revealed that miRNA regulation of a single gene can improve synaptic plasticity and memory, alter bone development, and affect various phenomenon in immune cells, including response to infection, proliferation of thymocytes, and derepression of cytidine deaminase activity." (PMID 41533591, 2026). "To investigate whether CDA‐producing strains can play a role in controlling infection in vivo, we challenged mice nasally with influenza A virus (IAV) after treatment with the relevant strains and evaluated their protective efficacy." (PMID 39588587, 2025). "Next, as V. inaequalis has eight putative CDA genes and, of these, ViCDA6 is upregulated during infection, while ViCDA1 is constitutively expressed in culture and in planta, it was hypothesized that V. inaequalis deacetylates chitin to chitosan during host colonization." (PMID 37039647, 2023). "To investigate whether A3G inhibits EV71 replication, we transfected A3G or its mutant C291S, which inactivates the cytidine deaminase of A3G, into HEK293T cells for 24 h and infected them with EV71 at a multiplicity of infection (MOI) of 1.0." (PMID 30247716, 2018). "In contrast, A3A was not packaged, and appeared to restrict infection in a largely CDA-independent manner." (PMID 24851906, 2014). "APOBEC3G is incorporated into HTLV-1 virions and inhibits the infection of HTLV-1 without exerting its cytidine deaminase activity." (PMID 15943885, 2005). "However, adaptive immune responses raised against PLV were not implicated in these differences, and G to A substitutions, due to cytidine deaminase activity, were also not found to be responsible for the bottleneck of FIV infection three weeks post-PLV infection." (PMID 29677149, 2018).
adenocarcinoma (2 papers, 2009 to 2022). A common cancer characterized by the presence of malignant glandular cells. "We also observed similar changes in CDA mRNA, protein and activity in two additional adenocarcinoma cell lines (breast and ovarian)." (PMID 19500405, 2009).
hematologic malignancies (2 papers, 2022 to 2023). "Constitutive low levels of CDA activity have been reported in the blood of patients with hematological malignancies or suffering from gemcitabine toxicity." (PMID 35982128, 2022). "Moreover, CDA activity levels are frequently low in patients with hematological malignancies, suggesting that this “poor metabolizer” phenotype may constitute a risk for blood cancers." (PMID 35982128, 2022). "Recently, an oral form of Decitabine in combination with cytidine deaminase (CDA) inhibitor Cedazuridine, termed C-DEC, has been approved as the first oral HMA, and its possible role in MDS and secondary AML along with other hematologic malignancies is of active interest." (PMID 37425516, 2023).
genetic diseases (1 paper, 2021). "Another major problem in applying CBEs to treat genetic diseases is that the target site must naturally exist in the preferred DNA sequence context for the cytidine deaminase, which may or may not be the case for the desired modification." (PMID 34171358, 2021).
psychiatric disorder (1 paper, 2024). A disorder characterized by behavioral and/or psychological abnormalities, often accompanied by physical symptoms. "Some studies have demonstrated that CDA gene expression in the brain is associated with certain psychiatric disorders by creating DNA mutations via deamination of cytosine bases, which results in uracil." (PMID 38375040, 2024).
CDA also shares sentences with these, for which no sentence is quoted: chronic myelomonocytic leukemia (4 papers); Autoimmunity (2); colorectal adenocarcinoma (2); adenomyosis (1); asthma (1); chondrosarcoma (1); chronic lymphocytic leukaemia (1); clear cell kidney carcinomas (1); colitis (1); congenital dyserythropoietic anemia (1); depression (1); diabetes (1); diffuse large B-cell lymphoma (1); esophageal (1); gallbladder cancer (1); glomerulonephritis (1); gout (1); head and neck cancer (1); head and neck squamous cell carcinoma (1); hemolytic neonatal anemia (1); hepatitis B virus infection (1); Hodgkins lymphoma (1); influenza (1); liver cancer (1); mesothelioma (1); metastatic melanoma (1); Myelodysplasia (1); Nasal polyposis (1); non-Hodgkin lymphoma (1); pancreatic adenosquamous carcinoma (1).
A further 11 diseases each share a sentence with CDA in 1 paper.